CAT (catalase)
Diseases named in the same sentence as CAT in open-access papers (continued):
Sharing a sentence is not in itself a finding about the gene and the disease.
aphthous stomatitis (1 paper, 2014). "In view of the lack of sufficient studies pertaining to this issue, the present study was undertaken to evaluate the serum levels of enzymatic antioxidants SOD, GPx, and CAT in patients with recurrent aphthous stomatitis." (PMID 25574385, 2014).
arteriosclerosis (1 paper, 2019). A vascular disorder characterized by thickening and hardening of the walls of the arteries. "It has been confirmed that the mitochondrial catalase overexpression can reduce the prevalence of arteriosclerosis and cataract in mice, and also protects against cardiovascular dysfunctions and injuries in human." (PMID 30858941, 2019).
asphyxia (1 paper, 2025). A state of general hypoxia and hypercapnia (abnormally elevated carbon dioxide (CO2) levels in the blood), resulting in acidosis, which affects all tissues in the body. "As oxygen decreased further, CAT activity declined steadily, reaching its lowest point in the asphyxia group (p < 0.05)." (PMID 41463861, 2025).
Ataxia (1 paper, 2025). Ataxia refers to impaired coordination of voluntary muscle movement. "Increased CAT activity was reported in studies related to ataxia and Nijmegen syndrome (NBS) syndrome." (PMID 40216824, 2025).
atrial fibrillation (1 paper, 2025). A disorder characterized by an electrocardiographic finding of a supraventricular arrhythmia characterized by the replacement of consistent P waves by rapid oscillations or fibrillatory waves that vary in size, shape and timing and are accompanied by an irregular ventricular response. "A murine model of atrial fibrillation exhibits cognitive and vascular dysfunction which is prevented by expression of mitochondrial catalase to reduce mitochondrial reactive oxygen species." (PMID 41055963, 2025).
Autoimmunity (1 paper, 2025). The occurrence of an immune reaction against the organism's own cells or tissues. "In turn, Cd increases ROS production, activates the NF-κB/MAPK pathway, impairs the antioxidant enzymes SOD, CAT, and GPx via Zn/Cu displacement, and promotes proinflammatory cytokines and autoimmunity." (PMID 40806618, 2025).
avascular necrosis (1 paper, 2022). Necrotic changes in the bone tissue due to interruption of blood supply. "This study detected five target genes (IL-1β, STAT3, CAT, PTGS2, and HMOX1) to further study the effects of quercetin, luteolin, kaempferol, cryptotanshinone, and naringenin on the expression of related genes in steroid-induced avascular necrosis of the femoral head." (PMID 35915795, 2022).
B-cell lymphoma (1 paper, 2025). "In this study, we found that LPS infection downregulated the catalase and B-cell lymphoma/Leukemia-2 expression levels, and upregulated B-cell lymphoma/Leukemia-2-associated X and cysteine-aspartic-specific protease-3 levels in S. prenanti." (PMID 40362113, 2025).
bacterial vaginosis (1 paper, 2011). Infection caused by bacterial overgrowth in the vagina. "H2O2 affects catalase-negative bacteria, but lactic acid and bacteriocins can affect catalase-negative as well as catalase-positive bacteria and Candida albicans specifically those responsible for bacterial vaginosis." (PMID 21960733, 2011).
Bell's palsy (1 paper, 2020). Partial or complete paralysis of the facial muscles of one side of a person's face. "In addition, the serum levels of malondialdehyde and the antioxidants glutathione, catalase, and superoxide dismutase were elevated in Bell’s palsy patients." (PMID 32144358, 2020).
biliary tract infections (1 paper, 2023). "One of its species, Catabacter hongkongensis, is a strictly anaerobic, catalase‐positive, motile, non‐sporulating, gram‐positive coccobacillus that mostly presents with gastrointestinal or biliary tract infections associated with a poor prognosis." (PMID 36284437, 2023).
bone sarcoma (1 paper, 2011). A sarcoma that arises from the bone. "The possible raised levels of hydrogen peroxide may explain the reduction in CAT observed in bone sarcoma patients, in this study." (PMID 21871117, 2011).
brain inflammation (1 paper, 2020). "Similarly, loading of catalase into EVs from RAW 264.7 macrophage cell line enhanced its stability and protective activity against oxidative stress in a mouse brain inflammation model." (PMID 32610582, 2020).
brucellosis (1 paper, 2023). Brucellosis is a bacterial infection that spreads from animals to people via unpasteurized dairy products or by exposure to contaminated animal products or infected animals. "Our research findings suggest that the inhibition of catalase by 3-AT enhances the host defense in murine brucellosis." (PMID 38139181, 2023). "However, catalase in the periplasm of Brucella also plays a crucial role in protecting the bacteria from H2O2 produced during the host cell’s response to brucellosis." (PMID 38139181, 2023). "Therefore, controlling the catalase activity may contribute to the management of brucellosis." (PMID 38139181, 2023).
C. perfringens infection (1 paper, 2025). "In the present study, compared to the NC group, the PC group exhibited an imbalance in redox homeostasis, with significantly lower activities of CAT and SOD, and the MDA concentration slightly increased, indicating a state of oxidative stress in broilers under C. perfringens infection." (PMID 40559850, 2025). "Compared to the NC group, the PC group decreased (p < 0.05) the CAT activity and exhibited a tendency toward higher MDA content; however, the groups with dietary supplementation of 40 or 80 mg Zn alleviated the changes in MDA induced by C. perfringens infection." (PMID 40559850, 2025).
Central obesity (1 paper, 2017). "In conclusion, men with abdominal obesity featured superoxide dismutase induction, and H2O2 accumulation in the visceral fat depot, despite upregulation of catalase activity." (PMID 28545081, 2017). "Central obesity did not alter these markers in subcutaneous fat, apart from a 50% increase in catalase, and did not affect glutathione peroxidase in either fat depot." (PMID 28545081, 2017).
cerebral cysts (1 paper, 2022). "In addition, an increase in CAT activity (p = 0.04) was observed in the presence of cerebral cysts, which confirms the data on a decrease in the OS level in newborns with late-onset FGR based on the background of increased antioxidant protection." (PMID 36670868, 2022).
Chlamydia infection (1 paper, 2017). "Intriguingly, other members of the Chlamydiaceae family have been shown to express functional catalase activity suggesting that ROS is an important host defence mechanism against Chlamydia infection and may limit the replicative ability of C. trachomatis within phagocytic cells such as macrophages." (PMID 28570638, 2017).
chondrosarcoma (1 paper, 2016). A malignant cartilaginous matrix-producing mesenchymal neoplasm arising from the bone and soft tissue. "Pretreatment of cells with DPI, catalase, or NAC abrogated the ACDB-induced ROS production and cell apoptosis, suggesting that ACDB-induced cell apoptosis involves ROS release in chondrosarcoma." (PMID 27835579, 2016). "We used catalase (H2O2 scavenging enzyme), NAC (a direct scavenger of ROS), and DPI (an NADPH oxidase inhibitor) to determine ACDB-increased cell apoptosis, indicating that ROS accumulation contributes to ACDB-induced cell death of human chondrosarcoma." (PMID 27835579, 2016).
chronic bronchitis (1 paper, 2019). A type of chronic obstructive pulmonary disease characterized by chronic inflammation in the bronchial tree that results in edema, mucus production, obstruction, and reduced airflow to and from the lung alveoli. "The results showed that Shashen Maidong Decoction (with G. littoralis as the main component) increased the activity of SOD, CAT, and GSH-PX and decreased the MDA content in the serum of rats with chronic bronchitis." (PMID 31915441, 2019). "In a study examining the antioxidant ability of Shashen Maidong Decoction in a chronic bronchitis rat model, pharmacodynamic experiments were conducted by examining the activity of SOD, CAT, glutathione peroxidase (GSH-PX), and MDA as indices." (PMID 31915441, 2019).
chronic hepatitis (1 paper, 2016). An active inflammatory process affecting the liver for more than six months. "A study comparing oxidative stress in chronic hepatitis patients with NAFLD patients showed that the MDA level and the GPx and SOD activities were elevated, while the CAT activity and the glutathione content were suppressed in the plasma of the NAFLD patients." (PMID 27019761, 2016).
chronic hepatitis B (1 paper, 2015). "Therefore, we further evaluate the association between these 3 widely studied CAT gene polymorphisms (rs1001179, rs769217, and rs7943316) and the risk of hepatitis B virus (HBV)-related HCC in addition to chronic hepatitis B (CHB) and HBV-liver cirrhosis (LC) in the Guangxi Chinese population." (PMID 25837767, 2015).
chronic lung disease (1 paper, 2022). According to the definitions of the American and British Thoracic Societies, including pulmonary functional tests, X-rays, and CT scans for items such as fibrosis, bronchiectasis, bullae, emphysema, nodular or lymphomatous abnormalities. "The list of antioxidants in breast milk that potentially protect against neonatal chronic lung disease includes more than ten elements (probiotics, phytochemicals, amino acids, trace elements, vitamins, Glutathione, oligosaccharides, catalase, melatonin, lactoferrin, among others)." (PMID 36291386, 2022).
cobalamin deficiency (1 paper, 2019). "Our results indicated that cobalamin deficiency led to the increase of catalase activity in astrocytes, whereas the activity of SOD and GPx was not affected in the treated cells." (PMID 31771278, 2019).
convulsion (1 paper, 2018). A rapid and repeated body muscle contract that results in an uncontrolled shaking of the body. "PTZ-induced convulsions in this study significantly reduced the levels of catalase and superoxide dismutase while increasing lipid peroxidation products, which is indicative of significant oxidative stress in the brain tissue." (PMID 29853980, 2018).
coronary atherosclerosis (1 paper, 2023). Atherosclerosis of the coronary vasculature. "Our finding is consistent with the study which showed that in the early stages of coronary atherosclerosis, SOD and CAT levels were increased and significantly were worsening with disease progression." (PMID 37511912, 2023).
cryptorchidism (1 paper, 2020). The failure of one or both testes of a male fetus to descend from the abdomen into the scrotum during the late part of pregnancy. "The occurrence of cryptorchism was associated with oxidative stress characterized in the right testis by a significant decrease (p < 0.05) in catalase and SOD activities and a high lipid peroxidation (increase in MDA)." (PMID 32670587, 2020). "In the present work, cryptorchidism was characterized by a high MDA concentration, low antioxidant enzyme (SOD and catalase) activities and a decrease in testicular protein levels." (PMID 32670587, 2020).
cutaneous papilloma (1 paper, 2021). "MDA may be a more sensitive indicator for cutaneous papilloma in cattle than SOD, CAT, and ceruloplasmin." (PMID 34722735, 2021).
enteritis (1 paper, 2023). Inflammation of the small intestine. "To assess the potential antioxidant properties of Ancientino in DSS-induced enteritis mice, we evaluated the activities of SOD, GSH-Px, CAT, and MDA levels in colon tissues." (PMID 37375702, 2023).
enteropathy (1 paper, 2017). "However, in the group of indomethacin-induced enteropathy, 2C3DHTA didn’t influence MDA concentration and SOD, CAT activities." (PMID 29064425, 2017).
Era (1 paper, 2025). "The protein expression levels of calponin-1, SM22α, and αSMA, and the mRNA expression levels of calponin-1, αSMA, SM-MHC, SOD, and CAT in the Era-induced group were significantly downregulated compared to those in the NC group." (PMID 39754271, 2025).
erysipelas (1 paper, 2017). An infection of the upper layers of the skin caused by species of streptococcus. "Currently, our knowledge on the association between SOD1, SOD2, and CAT gene expression and severity of erysipelas is limited." (PMID 28512644, 2017). "The presence of SOD1 G7958, SOD2 T2734, and CAT C262 alleles was linked to erysipelas' predisposition." (PMID 28512644, 2017). "Therefore, we sought to determine whether single-nucleotide polymorphisms (SNPs) in the genes encoding SOD1, SOD2, CAT, and cytokine levels and their interaction can serve as susceptibility markers for erysipelas." (PMID 28512644, 2017). "There were lack of differences in the distribution of SOD1 (G7958A), SOD2 (T2734C), SOD2 (C60T), and CAT (C262T) SNPs in subjects with erysipelas based on gender, multiplicity, and severity of the disease (p > 0.05)." (PMID 28512644, 2017). "Comparing 71 erysipelas patients to 55 age-matched healthy individuals, we sought for CAT, SOD1, and SOD2 single polymorphism mutation (SNPs) interactions with erysipelas' predisposition and serum cytokine levels in the acute and recovery phases of erysipelas infection." (PMID 28512644, 2017). "Also, correlation between expression of SOD1, SOD2, and catalase genes and activation of inflammatory cytokine in erysipelas still remain unknown." (PMID 28512644, 2017). "Erysipelas patients were grouped based on the identified SNPs in SOD T2734C and CAT C262T." (PMID 28512644, 2017).
exfoliation syndrome (1 paper, 2010). An autosomal dominant disorder caused by mutations in the LOXL1 gene, encoding lysyl oxidase homolog 1. "Several studies implicate oxidative stress as contributory to exfoliation syndrome, including the observation that aqueous humor from exfoliation syndrome patients has decreased levels of catalase activity." (PMID 20617205, 2010).
follicular thyroid cancer (1 paper, 2024). "These authors observed a reduction in Sod2-to-Gpx1 and Sod2-to-catalase ratios in DRP-TpoKO mice (follicular thyroid cancer model), indicating an inability to scavenge ROS." (PMID 39125641, 2024).
Friedreich ataxia (1 paper, 2020). An inherited condition that affects the nervous system and causes movement problems. "MSCs secrete CAT and upregulation of CAT expression is associated with the therapeutic properties of MSCS in models of Friedreich's ataxia, radiation‐induced aortic injury, septic lung injury, and hepatoxicity." (PMID 32497410, 2020).
gallbladder cancer (1 paper, 2012). "Native PAGE was also evaluated to analyze lactate dehydrogenase (LDH), superoxide dismutase (SOD) and catalase enzyme activity from the same blood of gallbladder cancer patients." (PMID 23009611, 2012). "The serum level of catalase was elevated in the patients with gallbladder cancer in our study." (PMID 23009611, 2012). "Increased activity of antioxidant enzymes, such as catalase, was observed while the activity of Mn-Zn-SOD was reduced in gallbladder cancer." (PMID 23009611, 2012).
gallstones (1 paper, 2025). Solid crystalline precipitates in the biliary tract, usually formed in the gallbladder, resulting in the condition of cholelithiasis. "The research by Tranum Kuar and others in North Indian Population has shown that levels of catalase, SOD, and glutathione-related enzymes were decreased in patients with gallstones in comparison to patients without gallstones, which can be attributed to increase oxidative stress." (PMID 40734667, 2025).
glomerulonephritis (1 paper, 2025). A renal disorder characterized by damage in the glomeruli. "In obese mice, treatment with Clo led to glomerulonephritis, which was associated with an infiltration of inflammatory cells, a reduced activity of antioxidant enzymes (SOD, CAT, GPx), and an increased concentration of ROS in the kidney." (PMID 41302104, 2025).
glucosuria (1 paper, 2021). "Additionally, since SGLT2i treatment leads to glucosuria, we performed a correlation analysis of glucosuria and antioxidant enzyme activity, which revealed significant positive correlations with respect to CAT, SOD, and MnSOD." (PMID 34336104, 2021).
Graves disease (1 paper, 2020). Graves' disease is an autoimmune disorder that leads to overactivity of the thyroid gland (hyperthyroidism).It is caused by an abnormal immune system response that causes the thyroid gland to produce too much thyroid hormones. "This study aims to evaluate the catalase (CAT) activity and the autoimmune response against the native CAT and the oxidatively modified enzyme in patients with Graves' disease (GD) and healthy controls in a comparative way." (PMID 31617239, 2020).
hematoma (1 paper, 2022). A hematoma is a collection of blood from a vascular structure into an extravascular space. "To access the oxidative accumulation and anti-oxidation effects on hematoma, we selected two antioxidant enzymes, SOD and CAT, and lipid peroxide MDA." (PMID 36071715, 2022).
hemochromatosis (1 paper, 2016). A disorder of iron metabolism characterized by a triad of HEMOSIDEROSIS; LIVER CIRRHOSIS; and DIABETES MELLITUS. "An epidemiological investigation reported that polymorphism in the catalase (CAT-rs2300181) gene and hemochromatosis (HFE) gene converted the association between ambient PM2.5 and total plasma homocysteine levels." (PMID 27463723, 2016).
hemophagocytic lymphohistiocytosis (1 paper, 2025). "Patients may be infected with various catalase-positive pathogens (e.g., Staphylococcus aureus, Aspergillus, Serratia, Burkholderia, Nocardia) and, in severe cases, may develop macrophage activation syndrome or hemophagocytic lymphohistiocytosis, complicating the diagnosis." (PMID 40538929, 2025).
herpesvirus infections (1 paper, 2023). "Unexpectedly, both enzymatic antioxidants (GPx and catalase) were noticeably higher during EEHV-HD, which differs from other studies that showed low levels of antioxidant enzymes associated with infectious diseases that cause hemorrhage, including other herpesvirus infections." (PMID 37174585, 2023).
hip fracture (1 paper, 2021). Traumatic or pathological injury to the hip in which the continuity of either the femoral head, femoral neck, intertrochanteric or subtrochanteric regions is broken. "According to the results of the present study, the increase of CAT activity in the hip fracture group, at the third and fourth time intervals, suggests that surgery caused generation of ROS and oxidative stress." (PMID 34211626, 2021).
hydatidosis (1 paper, 2019). "In this work, GSH-PX and SOD serum activities decreased significantly in hydatidosis infected sheep, while CAT activity significantly decreased in hydatidosis-infected cattle and buffaloes." (PMID 31528024, 2019). "However, GSH-PX, SOD, and CAT serum activities were lower in hydatidosis-infected camels." (PMID 31528024, 2019). "The effect of hydatidosis on serum GSH-PX, SOD, and CAT activities in sheep, cattle, buffaloes, and camels was studied." (PMID 31528024, 2019). "Serum GSH-PX, SOD, and CAT activities in hydatidosis infected and non-infected sheep, cattle, buffaloes, and camels." (PMID 31528024, 2019).